RNU6-1016P (RNA, U6 small nuclear 1016, pseudogene)
Gene: Small nuclear RNA gene on chromosome 6 (75,644,084 to 75,644,177, forward strand). Ensembl gene ENSG00000252498.
Homologues: Orthologues: chimpanzee U6 (100% identical), macaque U6 (99% identical), dog U6 (76% identical), dog U6 (69% identical), mouse Gm55405 (63% identical). Paralogues in human: RNU6-1060P (84% identical), RNU6-125P (84% identical), RNU6-1263P (84% identical), RNU6-15P (84% identical), RNU6-463P (84% identical), RNU6-10P (83% identical), RNU6-1122P (83% identical), RNU6-116P (83% identical), RNU6-1266P (83% identical), RNU6-33P (83% identical), RNU6-1 (82% identical), RNU6-1011P (82% identical), and 1288 more.